EGFR (epidermal growth factor receptor)
Diseases named in the same sentence as EGFR in open-access papers (continued):
Sharing a sentence is not in itself a finding about the gene and the disease.
cancer (continued). "These mutations increase the kinase activity of EGFR and eliminate the dependence of the cancer mutants on EGF binding for activation, leading to stimulation of downstream pro-survival and cell-growth pathways, and consequently conferring oncogenic properties on EGFR." (PMID 34319231, 2021). "Thus, SGLT1 targeting or dual SGLT1/2 inhibition may also serve as novel anti-cancer strategies due to ROS reduction and the disruption of SGLT1/EGFR interaction." (PMID 34439414, 2021). "To date, SDF-1/CXCR7 signaling via EGFR has not been established in a cancer model." (PMID 34067095, 2021). "Together with recent findings that the depletion of GGA2 suppresses cell proliferation in ARPE-19, and two NSCLC-derived cancer cell lines, PC9 and H1975, it is most likely that both AP-1 and GGA2 have a fundamental influence on cell growth by sustaining the expression of EGFR." (PMID 34799560, 2021). "However, A431 has the lowest average diffusion coefficient shift among cancer cell lines, whereas Skbr3 and Skov3 have the highest average shifts, indicating the reason that the expression level of EGFR does not thoroughly control its activation." (PMID 33603128, 2021). "Unlike drug resistance that occurs in EGFR mutation-driven cancers or BCR-Abl-induced leukemia, secondary mutations such as gate-keeper mutations that cause drug resistance are rare in BRAF(V600E)-driven cancers." (PMID 35582307, 2021). "In addition to HCC cells, similar interaction between STEAP3 and EGFR was observed in HEK293, suggesting it might be a common functional role of STEAP3 in human cancers." (PMID 34741044, 2021). "The clinical efficacy of combination treatment with anti-EGFR therapy might vary with different signaling activation levels and cell contexts in the TME as well as the timing of medication, tolerable toxicity, and different subsets of patients with cancer." (PMID 34884633, 2021). "Therefore, upon TKI-mediating EGFR inhibition, cancer cells rapidly upregulate Shh signaling to compensate for the absence of EGFR signaling." (PMID 34970481, 2021). "Through the analysis of cancer cell line pharmacogenomics datasets, we showed that the INT-CDC signature was also predictive of higher sensitivity to tyrosine kinase inhibitors (TKIs), including EGFR, ABL, and IGFR signaling inhibitors, and to SRC and MAPK signaling inhibitors." (PMID 34200770, 2021). "Therefore, the development of EGFR-targeting drugs to interrupt its signaling, either by blocking the EGF binding site or inhibiting its tyrosine kinase activity, is a promising approach for cancer therapy." (PMID 33707468, 2021). "There was no metastatic tropism of MET-amplified cancer during progression after EGFR-TKI therapy." (PMID 34205733, 2021). "However, alternative receptor tyrosine kinases (EGFR, MET, HER2), post-translational processes (such as SUMOylation), IGF1R-EMT-independent pathways, and cancer–cell microenvironment interactions suggest that current preclinical models do not fully recapitulate the complex clinical scenario." (PMID 34065119, 2021). "However, overexpression of EGFR does not imply dependence of cancer cells on this receptor for oncogenic signaling." (PMID 33923200, 2021).
cancer (continued). "Similarly, the CB1 receptor antagonist AM251 up-regulates the expression rate and signaling of epidermal growth factor receptor (EGFR) via a CB1 receptor-independent pathway involving the destabilization of ER related α (ERRα) in PANC-1 and HCT116 cancer cell lines." (PMID 33478092, 2021). "However, one alectinib-resistant cancer did not feature resistance to ALK, yet, a PIK3CA G106V mutation was found, known to be linked to EGFR inhibitor treatment resistance in EGFR-mutant NSCLC." (PMID 33572278, 2021). "Interestingly, rhein can inhibit EGFR, the upstream modulator of COX-2 in cancer cells." (PMID 34257692, 2021). "However, the expression of EGFR was significantly reduced on cancer cells co-cultured with MSCs, and PD-L1 was increased on cancer cells not cultured with MSCs following treatment." (PMID 34885111, 2021). "We observed that most residues forming the X-pocket in EGFR were nonconservative, while K867, S895, and K960 were only present in EGFR, thereby offering the opportunity to utilize these residues to achieve selectivity among critical anti-cancer kinase targets." (PMID 34070173, 2021). "Likewise, neither fusion toxin affected the viability of the three EGFR– human cancer cell lines up to 10−8 m concentration." (PMID 33540470, 2021). "The modulation and role of DR4 in EGFR-targeted cancer therapy has not previously been reported." (PMID 33664875, 2021). "This is a broad family that includes four components, EGFR (HER1), HER2, HER3 and HER4, and is assigned to receptor tyrosine kinase (RTK) type I. It has an important role in the control of key signaling pathways that are related to cancer-cell growth, proliferation, migration and survival." (PMID 34683830, 2021). "Several studies also suggest that EGFR inhibition might be more effective in HPV Negative cancers than in HPV-positive cancers." (PMID 34430119, 2021). "It is currently not clear whether SHP2 regulated cancer stemness contributes to the drug resistance to EGFR-TKIs." (PMID 34217295, 2021). "Nonetheless, previous in vitro studies as well as clinical observations have suggested that EGFR signaling may affect cell migration in a cell type-dependent manner and not all cancer cells express EGFR." (PMID 34439567, 2021). "Provided that EGFR signaling activates many pathways associated with carcinogenesis and metastasis, such as MAPK, PI3K, and JAK-STAT, it is no surprise that it has made an attractive target for cancer therapy." (PMID 34591244, 2021). "One possible underlying mechanism for the lack of response to ICI treatment in cancers expressing mutant forms of the EGFR might be related to an enhanced expansion of Treg populations." (PMID 35052732, 2021). "The triggering of EGFR/PI3K/Akt signaling cascade has been previously observed in response to PAR1 stimulation and this is in line with several observations supporting a central role of this pathway in mediating the malignant progression of several human cancers." (PMID 33093643, 2021). "Moreover, the development of dual-inhibitors targeting EGFR and VEGFR2 has recently become a promising strategy for the treatment of diverse types of cancer to overcome problematic drug resistance and low response to selective tyrosine kinase inhibitors (TKIs) and to produce a synergistic effect." (PMID 34187263, 2021). "Indeed, normal cells and cancer cells would both secrete exosomes that containing EGFR (data not shown)." (PMID 33461557, 2021). "It is known that KRas mutant cancers are not dependent on EGFR signaling." (PMID 34853306, 2021). "In cancer samples, we found the confounding effect of EGFR itself was not significant." (PMID 33741950, 2021).
cancer (continued). "In addition to controlling glucose metabolism, PKM2 also regulates hypoxia-inducible factor-1α (HIF-1α), β-catenin (β-cat), epidermal growth factor (EGFR), signal transductors, transcriptional activators 3 (STAT3), and other cancer-related factors, thereby promoting cell growth and proliferation." (PMID 33905408, 2021). "Moreover, EGFR-TKI (e.g. apatinib and rapamycin) enhanced the chemosensitivity of cancer 43, 44, which suggested that anlotinib could increase the sensitivity of CRC cells to OXA." (PMID 33754008, 2021). "Strictly controlled by NIR light, GE11 peptide modified and CUR/ICG-loaded LPs (GE11-CUR/ICG-LPs) could introduce hyperthermia in EGFR overexpressed A549 cancer cells for photothermal therapy, which could also trigger the increased release of CUR for enhanced cancer cell inhibition." (PMID 33868396, 2021). "The discovery of a single compound that has both epidermal growth factor receptor (EGFR) kinase and tubulin polymerization inhibitory capabilities was spurred by clinical evidence for the efficacy of tyrosine kinase inhibitors in combination with microtubule-targeting medicines in cancer therapy." (PMID 34832895, 2021). "Since the ERBB2-expressing cancer cell lines, BT474, SKBR3, MDA-MB-361, MCF7, and OE19, used by the other studies also express EGFR, the lapatinib-induced autophagy promotion reported by these studies may be due to lapatinib inhibition of EGFR." (PMID 33801244, 2021). "Studies showed culturing cancer cells in polyhema coated dishes resulted in epithelial–messenchymal features switch from E-cadherin to N-cadherin, enhanced expression of oncogenic markers such as Slug, PI3K, AKT, ERK, EGFR, HER1 among other growth factors and receptors." (PMID 35054435, 2021). "The effect of Pan-HER has been investigated in a number of cell lines and xenografts representing a diverse number of cancer types including head and neck, lung, HER2+ breast, and other malignancies shown to have a dependency on one or more of the targets, i.e., EGFR, HER2, or HER3." (PMID 32414394, 2020). "Furthermore, we found that the membrane proteins CDH2, EGFR, ITGA3, ITGA5, ITGB1, and CALR may have significant effect on cancer prognosis and outcomes, which were further validated in vitro." (PMID 33005184, 2020). "Further, TRPV1 initiates direct negative feedback on the EGFR, and blocking EGFR may keep cancer cells from developing and growing." (PMID 33379302, 2020). "Higher non-synonymous TMB correlates with inferior PFS for first-generation EGFR-TKIs in EGFR-driven patients and worse response to pemetrexed/platinum regimen in EGFR/ALK wild-type patients, which has potential clinical implications for cancer treatment but needs corroboration in larger studies." (PMID 32411590, 2020). "Indeed, we observed that amplification of the EGFR gene region was rare to absent in HPV-positive cancers, while about half of the HPV-negative cases possessed different degrees of amplifications in the TCGA HNSC dataset." (PMID 32775042, 2020). "However, approximately 30% of EGFR-mutant cancers exhibit resistance to TKI treatment without well-known secondary EGFR mutations such as T790M7." (PMID 32277151, 2020). "The pathway analysis of autophagy gene concluding EGFR tyrosine kinase inhibitor resistance, human cytomegalovirus infection, PD-1 checkpoint pathway in cancer, and HIF-1 signaling pathway further confirmed the correlation between autophagy gene and malignant tumor." (PMID 33133307, 2020). "In addition, epidermal growth factor receptor (EGFR) has been shown to be involved in pathogenesis and progression of cancer, and the cytokine-receptor interaction signaling pathway is an important pathway in the development of cancer." (PMID 32462020, 2020).
cancer (continued). "Furthermore, Wnt/β-catenin signaling orchestrates multiple cell signaling cascades, such as epidermal growth factor receptor (EGFR), Hippo/YAP, nuclear factor kappa-B (NF-κB), Notch, Sonic Hedgehog and PI3K/Akt pathway, which contribute to pivotal molecular mechanism in cancer development." (PMID 33276800, 2020). "The patient’s basophils were not activated by the anti-EGFR mAb, cetuximab, which has been widely reported to trigger hypersensitivity reactions in a subset of cancer patients who have IgE antibodies against galactose-alpha-1,3-galactose (alpha-gal), that decorates cetuximab." (PMID 32645919, 2020). "Moreover, a subgroup analysis showed no benefit with erlotinib treatment also in patients with EGFR positive cancers, probably due to the small sample size." (PMID 36046069, 2020). "However, the existence of VEGF up-regulation independent of EGFR leads to cancer cell resistance to anti-EGFR." (PMID 33096664, 2020). "Specifically, CTD-2218G20.2 was predicted to interact with 86 proteins (Pearson correlation coefficient, PCC > 0.3), some of which, including PSG4, PSG5, and PSG7, could also interact with cancer-related proteins, including KISS1, TIMP2, MMP11, IGFBP1, EGFR, and CDKN1C." (PMID 32117443, 2020). "Epidermal growth factor receptor (EGFR), a member of the HER family of receptor tyrosine kinases, is abnormally expressed and activated in many epithelial tumors and plays a critical role in the initiation and development of cancer via modulating downstream signaling pathways." (PMID 33313320, 2020). "Furthermore, in a phase II study, the CRPC patients showed no response to Gefitinib (another EGFR inhibitor), which showed a minimum anti-cancer activity." (PMID 33224867, 2020). "Several independent research groups have reported cancer to non-cancerous cell transfer of EGFR." (PMID 33143170, 2020). "NE can activate the extracellular transactivation of membrane receptors such as epidermal growth factor receptor (EGFR) and Toll-like receptor 4 (TLR4), inducing mitogen activated protein kinase (MAPK) signaling and downstream effects, thereby directly promoting cancer cell proliferation." (PMID 33042821, 2020). "Vandetanib’s inhibition of viral egress could theoretically be related to its known ability to inhibit receptor tyrosine kinases such as epidermal growth factor receptor (EGFR) and vascular endothelial growth factor receptor (VEGFR), which is why it is FDA approved to treat certain cancers." (PMID 33173007, 2020). "Increased P2X7 expression correlates with expression of epidermal growth factor receptor (EGFR) and estrogen receptor (ER)α, which are well known drivers of cancer cell proliferation, suggesting that P2X7 might cooperate with these receptors to promote cell proliferation." (PMID 32581786, 2020). "Thus, the role of the type of N-glycan branching on EGFR, as well as of GOLPH3 in this process, could be different in different cancer cell lines." (PMID 33238647, 2020). "Here, we review our current understanding of the potential of AnxA6 as a biomarker for cancer diagnosis, the poor response of TNBC to EGFR-targeted therapies, and the prospects for the detection of AnxA6 as a predictor of the response of TNBC to EGFR-targeted therapies." (PMID 32784650, 2020). "Signal transduction through EGFR also activates the phosphatidylinositol-3-kinase (PI3K)/protein kinase B (AKT)/mammalian target of rapamicine (mTOR) signalling cascade, which is critical to cell survival, motility, and invasion, thus further promoting cancer survival and progression." (PMID 32413973, 2020). "Thus, in many cancer types, the Ras pathway activates downstream effector by stimulating platelet-derived growth factor receptor (PDGFR) and epidermal growth factor receptor (EGFR), e.g., phosphatidylinositol 3-kinase (PI3K), inositol triphosphate (PIP3), and Rac1." (PMID 33096860, 2020).
cancer (continued). "Therefore, a therapeutic approach targeting EGFR and VEGFR2 simultaneously may improve the outcome of cancer treatment." (PMID 33096664, 2020). "Interestingly, EGFR inhibition did not improve the anti-cancer effect of paclitaxel, a major chemo-therapeutic drug for the clinical treatment of BLBC, suggesting that EGFR inhibition only targets specific feedback signalling." (PMID 31937753, 2020). "Increased radioresistance of cancer cells is developed by the activation of several compensatory pro-survival cell signaling pathways, including phosphatidylinositol 3-kinase (PI3K)/AKT/mTOR pathway, EGFR/mitogen-activated protein kinase (MAPK) pathway and NF-κB signaling pathway." (PMID 32983997, 2020). "The obtained results highlight the importance of ERβ/EGFR crosstalk in the modulation of critical cell functional properties (i.e., invasion and adhesion), as well as the mRNA expression and gelatinolytic activity of matrix macromolecules (MMPs) involved in ECM remodeling and cancer progression." (PMID 33050027, 2020). "In the past decade, important clinical advances in cancer treatments are attributed to molecularly targeted treatments aiming at specific genes such as estrogen receptor alpha (ER-α), the human epidermal growth factor receptor 2 (HER2), the epidermal growth factor receptor (EGFR), etc." (PMID 31797627, 2020). "Our findings propose that EGFR is an attractive therapeutic target in chemoresistant EOC to be exploited in translational oncology, and erlotinib/cisplatin combination treatment is a potential anti-cancer approach to overcome chemoresistance and inhibit the proliferation of the EOC cells." (PMID 32660222, 2020). "Glazer investigated an in vitro model of mixed cancer cell populations to determine the synergy between RF cadmium-selenide and indium-gallium-phosphide quantum dots or gold NPs, all conjugated with CD225 antibody, to target epidermal growth factor receptor (EGFR)." (PMID 34138198, 2020). "This defines a genetic resistance-gap in patients with acquired resistance to chemotherapy and EGFR-Abs, similar to the 64% of the cancer cells sampled by ctDNA that had no detectable genetic resistance drivers observed in patients treated with single-agent cetuximab." (PMID 33322618, 2020). "However, there is no report that CD148 can inhibit malignant phenotypes of cancer cells by EGFR dephosphorylation." (PMID 32201537, 2020). "Moreover, some existing data show that, the longer PFS is not correlated with the longer OS among cancer patients who receive targeted drug therapy, like the anti-EGFR therapy." (PMID 33243184, 2020). "Many cancer and metabolism related networks were found to be involved after treatment with the drugs but only two pathways were altered by the combination treatment and not by MP or rapamycin alone: the MAPK and the epidermal growth factor receptor (ErbB) signaling pathways." (PMID 32776229, 2020). "However, the EGFR inhibitor blocked MM1-CM- and COM-CM-induced cancer cell invasion effectively." (PMID 32731484, 2020). "Considering the close relationships between SG and cancer development, we hypothesized that ATXN2L might participate in stress-related cancer malignant activities, which probably implies chemoresistance and EGFR signaling." (PMID 30787271, 2019). "Abnormal EGFR and PTEN signaling pathways may produce malignant tumors." (PMID 30863440, 2019). "More importantly, the gain-of-DEDD drives a previously unknown cancer-specific vulnerability to CDK4/6 targeting agents in combination with EGFR inhibitors, regardless of the Rb status of the TNBC cells." (PMID 31253784, 2019). "An examination of data from the Genomics Drug Sensitivity in Cancer project showed that the half maximal inhibitory concentration (IC50) values for Gefitinib (a tyrosine kinase inhibitor, TKI) and for Cetuximab (an anti-EGFR antibody) are significantly lower in basal as compared to non-basal cells." (PMID 31181806, 2019).